TREM1 (triggering receptor expressed on myeloid cells 1)
Diseases named in the same sentence as TREM1 in open-access papers (continued):
Sharing a sentence is not in itself a finding about the gene and the disease.
COVID-19 (26 papers, 2021 to 2026). A disease caused by infection with severe acute respiratory syndrome coronavirus 2. "For instance, high levels of TREM-1, a marker of innate immune response, have been associated with disease severity, duration of mechanical ventilation, and clinical outcomes in COVID-19." (PMID 38383504, 2024). "Our data suggest that the TREM-1 pathway is involved in the hyperinflammatory response and is associated with adverse outcomes in COVID-19." (PMID 34195785, 2021). "In the blood of COVID-19 patients, we observed a greater association of surface expression of TREM-1 with CD14−CD16+ than CD14+ cells." (PMID 34960790, 2021). "Observational data confirm that the TREM-1 pathway is activated and associated with subsequent disease severity, prolonged duration of mechanical ventilation and outcome, in COVID-19 and non COVID-19 ARDS." (PMID 37350989, 2023). "Activation of the TREM-1 pathway is associated with outcome in life threatening COVID-19." (PMID 37350989, 2023). "In addition, observational studies in patients admitted to hospital with COVID-19 have shown an association between the degree of TREM-1 activation, the development of severe disease and ultimate outcome." (PMID 37350989, 2023). "Therefore, it could be speculated that TREM-1 inhibition is a therapeutic target in COVID-19, and underlines the potential of a clinical trial of anti-TREM-1 treatment in patients with COVID-19, which is underway." (PMID 34195785, 2021). "The TREM-1 pathway inhibitor, nangibotide, was shown in a clinical trial to enhance clinical condition and reduce mortality among patients with severe COVID-19 who had high sTREM-1 levels." (PMID 41226426, 2025). "A clinical trial (NCT04544891) was conducted to evaluate the relationship between TREM-1 pathway activation, disease progression, and clinical outcomes in hospitalized COVID-19 patients." (PMID 41226426, 2025). "Recent clinical trials in septic shock and COVID-19 have demonstrated that nangibotide, a TREM-1 specific inhibitor, was safe and holds potential to improve clinical status." (PMID 40715696, 2025). "In contrast, inflammatory mediators associated with severe COVID-19 including CXCL-8, TREM-1 are increased with age." (PMID 38515147, 2024). "Observational data supports a potential role for TREM-1 in the pathophysiology of severe COVID-19 and ARDS in general." (PMID 37350989, 2023). "This study demonstrates that the TREM-1 pathway is activated in COVID-19 patients and that its magnitude of activation, appreciated by the measurement of plasma sTREM-1 concentration, is an important driver of the outcome." (PMID 37574520, 2023). "Complementarily, among several immunological markers, TREM-1, a receptor expressed mainly on the neutrophil’s surface, has also been studied in COVID-19 and other chronic inflammatory diseases as an important target contributing to hyperinflammation." (PMID 37626613, 2023). "The use of a TREM-1 modulatory strategy in COVID-19 was based upon existing preclinical and clinical proof of concept." (PMID 37350989, 2023). "Whilst the study was stopped early due to low recruitment rate, the ESSENTIAL study demonstrated that TREM-1 modulation with nangibotide is safe in COVID-19, and results in a consistent pattern of improved clinical status and mortality compared to placebo." (PMID 37350989, 2023). "MMP-8 is also relevant to COVID-19, as its target (triggering receptors expressed on myeloid cells-1) TREM1 correlates with the severity of COVID-19 patients." (PMID 35563537, 2022). "TREM-2 mRNA expression was substantially up-regulated in the PBMCs of patients with COVID-19 compared with the healthy group, while expression of TREM-1, TLT1, TLT2, and TLT4 was slightly increased." (PMID 34878838, 2021). "The frequency of CD14−CD16+TREM-1+ also increased on blood cell surfaces from moderate to critical COVID-19 groups compared to control and mild disease." (PMID 34960790, 2021).
COVID-19 (continued). "Next, we determined the expression of TREM-1 on the peripheral blood cell surface of patients with COVID-19 [mild (n = 15), moderate (n = 15), severe (n = 15), and critical (n = 11)] and healthy controls (n = 10)." (PMID 34960790, 2021). "TREM-1 was most highly expressed in mo 1 and mo int and significantly upregulated in mo 2 of COVID-19 patients." (PMID 34614036, 2021). "Indeed, TREM-1 inhibition in those with severe COVID-19 demonstrated a trend toward reduction in 28-day mortality in a phase 2 randomized controlled trial." (PMID 38383504, 2024). "We here aim to decipher whether plasma concentration of the soluble form of TREM-1 (sTREM-1) could predict the outcome of hospitalized COVID-19 patients." (PMID 37574520, 2023). "When these significant outcomes were adjusted for sex and age, only the frequency of NK cells (p-adjusted = 0.04), the MFI of CD274 on monocytes (p-adjusted = 0.03) and the MFI of TREM-1+ on HD neutrophils (p-adjusted = 0.03) remained significantly increased in OB patients with severe COVID-19." (PMID 37626613, 2023). "This suggests that the TREM-1 pathway is involved in the inflammatory reaction and the disease course of COVID-19, and therefore may be considered as a therapeutic target in severely ill patients with COVID-19." (PMID 34195785, 2021). "Our data demonstrated strong enrichment of CCL2/19/20, CXCL10, GM-CSF, IL-6/8/15, S100A9, SCGF, TNF and TREM-1 in COVID-19, which could potentially play a critical role on the pathogenesis of the disease." (PMID 34238349, 2021). "This might suggest a link between TREM-1 activation and the increased incidence of thromboembolic events seen in COVID-19, which is also supported by our data." (PMID 34195785, 2021). "Our data add to the hypothesis that anti-TREM-1 therapy could be effective in severely ill patients with COVID-19." (PMID 34195785, 2021). "Critical COVID-19 is distinguished by very high levels of IL-1β and T lymphocyte activation (including IL-7), whereas septic shock displays higher levels of IL-6, IL-8 and a more significant myeloid response (including TREM-1 and IL-1ra)." (PMID 35111777, 2021). "In this context, because the triggering-receptor expressed on myeloid cells-1 (TREM-1) is considered an intrinsic amplifier of inflammatory signals, this study investigated the role of soluble TREM-1 (sTREM-1) as a biomarker of the severity and mortality of COVID-19." (PMID 34960790, 2021). "Small studies suggest that TREM-1 could be involved in viral infections, including COVID-19." (PMID 37574520, 2023). "However, the role of neutrophils in the TREM-1 pathway during COVID-19 needs further study." (PMID 34960790, 2021). "Furthermore, we assess whether patients with COVID-19 could be stratified based on sTREM-1 plasma concentrations and therefore could possibly benefit from anti-TREM-1-therapy." (PMID 34195785, 2021). "Given that SARS-CoV-2 induces a hyper-inflammatory response, we hypothesized that in COVID-19 patients, the virus could trigger activation and up-regulation of TREM-1 in the cell surface and, subsequently, shedding in the soluble form (sTREM-1) by metalloproteinase activity." (PMID 34960790, 2021). "Furthermore, the percentages of CD14+TREM-1+ were lower in those COVID-19 patients." (PMID 34960790, 2021). "CD163 and TREM-1 levels were relatively low in both viral CAP groups (CAP-flu and COVID-19), although only significant in the latter group." (PMID 35660785, 2022). "Therefore, TREM-1 modulation might have clinical benefits in patients with COVID-19." (PMID 34195785, 2021). "Whether the TREM-1 pathway has either diagnostic or therapeutic value in COVID-19 is not yet known." (PMID 34195785, 2021). "We observed that the reduction in the expression of TREM-1 on the cell surface in CD14+ and CD16+ leukocytes from the blood of COVID-19 patients was accompanied by a concomitant increase in plasma levels of sTREM-1." (PMID 34960790, 2021).
COVID-19 (continued). "While the role of sTREM-1 in patients presenting severe COVID-19 remains unclear, a functional genomic analysis of PBMCs from individuals undergoing infection with enterovirus A71 (EV-A71) determined that activation of TREM-1 was correlated with clinical severity." (PMID 34960790, 2021). "Specifically, the frequency of peripheral NK cells, the expression of PD-L1 on CD14+ monocytes, and TREM-1 on CD11b+ HD neutrophils were the major discriminators between OB and N-OB patients with severe COVID-19, regardless of age and sex." (PMID 37626613, 2023). "For example, TREM1 Signalling (z-score = 3.157; BH p-value = 3.162 × 10–02), STAT3 Pathway (z-score = 0.949; BH p-value = 7.762 × 10–03) and IL-22 signalling (z-score = 1.732; BH p-value = 2.239 × 10–02) were all amongst the pathways upregulated in severe COVID-19 compared to mild COVID-19." (PMID 35844004, 2022).
inflammatory bowel disease (26 papers, 2011 to 2025). A spectrum of small and large bowel inflammatory diseases of unknown etiology. "TREM1 has been implicated in multiple pathological conditions including stroke, myocardial infarction, and inflammatory bowel diseases." (PMID 34721438, 2021). "Moreover, triggering receptor expressed on myeloid cells 1 (TREM1)+ Mφ are key pathogenic cell subsets that significantly amplify chronic inflammation in inflammatory bowel disease (IBD)." (PMID 41318555, 2025). "Partially consistent with a previous study, intestinal mucosa barrier damage in pancreatitis-associated inflammatory bowel disease models could be ameliorated by TREM1 blockade LP17 treatment." (PMID 33954188, 2021). "Alterations in TREM receptors (TREM-1/2) are emerging as key components associated with inflammatory bowel disease (IBD) and neurodegenerative disorders spreading inflammation through the gut-brain-axis namely microbiota dysbiosis, leaky gut, and inflammation." (PMID 33927630, 2021). "The expression of Triggering Receptor Expressed on Myeloid cells (TREM)-1 has been described as a predictive marker for anti-Tumor Necrosis Factor (TNF)-α monoclonal antibody (mAb) therapy responsiveness in patients with inflammatory bowel disease (IBD)." (PMID 33790898, 2021). "As in previous studies, it has been confirmed that TREM1 participates in inflammatory bowel diseases." (PMID 33954188, 2021). "Considering the role of TREM-1 in gastroenteric inflammatory diseases, such as in inflammatory bowel disease, celiac disease, and NV infection, we hypothesized that the receptor might play a role in RV infection." (PMID 41156639, 2025). "TREM1 was initially found to play a crucial part in septic inflammation and was later identified by mounting evidence as a mediator of inflammatory response in various diseases including inflammatory bowel disease and spinal cord injury." (PMID 35100093, 2022). "More recent data have linked TREM-1 to inflammatory bowel disease, pancreatitis and other non-infectious conditions, calling the idea of a specificity of the TREM-1 pathway into question." (PMID 27116911, 2016). "However, these are acute inflammatory models and a similar role has been described for TREM1 in other chronic inflammatory diseases, such as Crohn’s disease, ulcerative colitis and inflammatory bowel disease, through the use of agonist TREM1." (PMID 25642940, 2015). "Alterations in Triggering Receptors Expressed on Myeloid cells (TREM-1/2) are bound to a variety of infectious, sterile inflammatory, and degenerative conditions, ranging from inflammatory bowel disease (IBD) to neurodegenerative disorders." (PMID 31546668, 2019). "Triggering receptor expressed on myeloid cells-1 (TREM-1) is highly expressed on macrophages in inflamed intestines and reportedly promotes inflammatory bowel disease (IBD) by augmenting pro-inflammatory responses." (PMID 31189465, 2019). "We have previously demonstrated that TREM-1-expressing cells accumulate in the inflamed intestinal mucosa of patients with inflammatory bowel diseases (IBD) and that TREM-1-mediated signaling critically contributes to intestinal inflammation." (PMID 29093489, 2017). "In the intestine, TREM-1 is highly expressed by macrophages, contributing to inflammatory bowel disease (IBD) pathogenesis." (PMID 25347935, 2014). "Thus, the blockade of TREM-1 with a soluble mTREM-1/IgG fusion protein reduces the TREM-1-mediated inflammatory response and the severity of infectious diseases, such as Pseudomonas aeruginosa-related keratitis, septic shock and inflammatory bowel disease (IBD)." (PMID 25464008, 2014). "Role of TREM-1 in inflammatory diseases, such as COPD, inflammation in vascular bed, inflammatory bowel disease and gastric ulcers, is well established." (PMID 27148736, 2016).
inflammatory bowel disease (continued). "More recent studies have found that TREM-1 mRNA and protein were elevated in inflammatory bowel disease, experimental colitis, inflammatory arthritis, and other noninfectious inflammatory diseases." (PMID 27083877, 2016).
lung carcinoma (23 papers, 2014 to 2025). "Considering enterovirus caused human respiratory illness, we also evaluated TREM-1 upregulation induced by EV-D68 in human fetal lung diploid fibroblasts (2BS) and human lung carcinoma (A549) cells." (PMID 34887856, 2021). "In lung cancer patients, TREM-1 expression is upregulated in tumor-associated macrophages and is correlated with clinical outcome." (PMID 31275318, 2019). "Cancer cells can directly upregulate TREM-1 expression in macrophages in lung cancer patients, and this is linked with cancer recurrence and poor survival of non-small cell lung cancer patients." (PMID 31275318, 2019). "TREM-1 is expressed in NK cells and its expression is associated with lung cancer progression in patients." (PMID 31275318, 2019). "Growing evidence points to a causal role of TREM-1 in chronic inflammation-mediated lung cancer." (PMID 32456204, 2020). "TREM-1 and sTREM-1 expression were recently studied in human lung cancer, especially in human non-small cell lung cancer (NSCLC), which represents over 80% of all lung cancers." (PMID 35875168, 2022). "Studies assessing TREM-1 and/or soluble TREM-1 (sTREM-1) expression in human solid malignancies (except digestive and lung cancers)." (PMID 35875168, 2022). "It was described that TREM1 promoted tumorigenesis and supported tumor growth in multiple tumor models, such as intestinal, pancreatic, and lung carcinomas." (PMID 34868341, 2021). "Lung cancer cells directly promoted TREM-1 upregulation, sTREM-1 release, and pro-inflammatory cytokine secretion in primary Mn/macrophages from NSCLC patients." (PMID 32456204, 2020). "Trigger receptor (TREM)-1, a member of the hyperimmunoglobulin family, is primarily expressed in monocytes/macrophages and is highly expressed in colon, liver, and lung cancer tissues." (PMID 33224886, 2020). "Co-culture of blood monocytes of these NSCLC patients with lung cancer cells resulted in TREM-1 upregulation in the monocytes, and in the same study inhibition of TREM-1 expression by shRNA was associated with decreased invasiveness of lung cancer cells." (PMID 32908142, 2020). "The expression of TREM-1 on TAMs decreases significantly with tumor growth, which is a feature of lung cancer TAMs." (PMID 33224886, 2020). "To investigate the role of TREM-1 in lung cancer, we studied the expression of TREM-1 in urethane-induced lung tumor tissues and B16F10 lung metastasis tumor tissues using western blotting and immunohistochemistry." (PMID 31275318, 2019). "In order to confirm the role of COX-2 in induction of TREM-1 we performed experiments where we co-cultured lung cancer cells with monocyte/macrophages for 48 hours in the presence of COX-2 inhibitors or vehicle treatment." (PMID 24842612, 2014). "Recent studies have shown that TREM-1 is highly expressed in colon, hepatocellular and lung carcinoma tissue." (PMID 24842612, 2014). "Since the expression of TREM-1 is restricted to myeloid cells we questioned which cell types express TREM-1 in lung cancer tissue." (PMID 24842612, 2014). "By employing an in vitro model we confirmed that expression of TREM-1 is increased in macrophages that are co-cultured with human lung cancer cells." (PMID 24842612, 2014). "A proposed five-gene diagnostic signature, including KRT5, MUC1, TREM1, C3, and TMPRSS2, as well as an eight-gene classifier for lung cancer subtypes, exhibited a high predictive accuracy of 0.936 during testing on 2556 adenocarcinoma samples and 1630 squamous cell carcinoma samples." (PMID 38612418, 2024). "Moreover, it is found that the expression of TREM-1 in tumors is closely related to tumor invasiveness of liver cancer and lung cancer." (PMID 33224886, 2020). "Mechanistically, lung cancer cells could induce increased expression of TREM-1 in macrophages through COX-2 signaling." (PMID 33224886, 2020).